ART1 (ADP-ribosyltransferase 1)
Diseases named in the same sentence as ART1 in open-access papers:
ART1 is named in the same sentence as 27 diseases in open-access papers, as found by Europe PMC text mining. Sharing a sentence is not in itself a finding about the gene and the disease. The quoted sentences say what the papers report.
colorectal cancer (5 papers, 2017 to 2025). A primary or metastatic malignant neoplasm that affects the colon or rectum. "This study is a preliminary investigation into the effects of ART1 on the IL-6-induced proliferation of colorectal cancer cells and its potential underlying mechanisms." (PMID 38504172, 2024). "Moreover, ART1 has been associated with enhanced tumor development and metastasis in colorectal cancer (CRC)." (PMID 40864788, 2025). "In addition, ART1 is associated with angiogenesis in human colorectal carcinoma tissues." (PMID 29069825, 2017). "Elevated expression levels of ART1 have been noted in colorectal cancer and glioblastoma, with its heightened expression correlating with unfavorable prognosis." (PMID 38911388, 2024). "In a murine model of colorectal cancer boasting a robust immune milieu, inhibition of ART1 has demonstrated efficacy in impeding tumor growth." (PMID 38911388, 2024). "Notably, the expression dynamics of ART1 exert profound regulatory effects encompassing crucial hallmarks of cancer progression, including proliferation, apoptosis, adhesion, migration, metastasis, and angiogenesis, particularly within the milieu of mouse colorectal cancer cells." (PMID 38911388, 2024). "The pro-carcinogenic effect that ART1 has in colorectal cancer was not seen in our Bladder TCGA analysis." (PMID 37895248, 2023).
colon carcinoma (3 papers, 2017 to 2024). "Our previous studies have shown that ART1 is associated with apoptosis, proliferation and migration of colon carcinoma CT26 cells." (PMID 29069825, 2017). "Immunofluorescence analyses confirmed the colocalization of ART1 and gp130 in the examined colon cancer cell lines." (PMID 38504172, 2024). "ART1 is up-regulated in CT26 colon cancer cells, and ART1 silencing reduces the survival rate and increases apoptosis." (PMID 30627052, 2019).
adrenocortical carcinoma (1 paper, 2024). "Leveraging the cBioPortal tool facilitated the assessment of the genetic modification status of ART1, revealing that mutations were predominantly prevalent in adrenocortical carcinoma (> 4%)." (PMID 38911388, 2024).
colitis (1 paper, 2024). Inflammation of the colon. "Notably, the current study revealed that ART1 knockdown significantly reduced p-STAT3 expression in transplanted tumours in a DSS-induced colitis mouse model." (PMID 38504172, 2024).
gastric cancer (1 paper, 2024). A primary or metastatic malignant neoplasm involving the stomach. "The results revealed a causal association between ART1 and STAD at the genetic level, further corroborating the potential role of ART1 in gastric cancer progression." (PMID 38911388, 2024). "Subsequently, to substantiate the cancer-promoting role of ART1 in gastric cancer, we performed experimental validation in vitro." (PMID 38911388, 2024).
glioma (1 paper, 2024). A benign or malignant brain and spinal cord tumor that arises from glial cells (astrocytes, oligodendrocytes, ependymal cells). "Although research regarding the effects of ART1 on cancer is limited, current experimental evidence suggests that ART1 plays an important role in hepatocellular carcinoma, glioma and CRC." (PMID 38504172, 2024).
Hypertension (1 paper, 2024). The presence of chronic increased pressure in the systemic arterial system. "In normal pregnancy, ART2 predominates, reducing hypertension, while ART1, which has a vasoconstrictor effect, increases in PE." (PMID 38794175, 2024).
lung adenocarcinoma (1 paper, 2007). A carcinoma that arises from the lung and is characterized by the presence of malignant glandular epithelial cells. "SPT7L has already been identified as a tumour-rejection antigen in lung adenocarcinoma (named ART1/P17) and, in good agreement with our results, described also as a subunit of the human STAGA complex (called STAF65γ)." (PMID 17375202, 2007).
lung carcinoma (1 paper, 2023). "Indeed, ART1 overexpression on lung cancer cells can enhance susceptibility to ART1-mediated ADP-ribosylation and to NICD in tumor-infiltrating P2 × 7R+CD8+ T cells, thereby constraining effective antitumor immunity and contributing to acquired resistance to immunotherapy." (PMID 37165408, 2023).
lymph node metastasis (1 paper, 2024). "The degree of positivity for ART1 and gp130 was related to the extent of lymph node metastasis and the pathological grade of the CRC tissues." (PMID 38504172, 2024). "The degree of positivity for ART1 and gp130 was related to the occurrence of lymph node metastasis and the pathological grade (P < 0.05)." (PMID 38504172, 2024).
Marfan syndrome (1 paper, 2022). A disorder of the connective tissue. "In Marfan syndrome, for example, the pathological changes in the aortic root are thought to be related to angiotensin II receptor 1 (ART1) signaling and the reverse-remodeling effects of losartan are mediated by blocking ART1 signaling and downstream TGF-β signaling." (PMID 36561772, 2022).
tumor (12 papers, 2007 to 2026). "ART1's associations with key markers of tumor proliferation and growth processes, including DNAss, RNAss, EREG.EXPss, EREG-METHss, DMPss, and ENHss, underscore its intricate involvement in tumorigenesis and tumor progression." (PMID 38911388, 2024). "Our exploration of the correlation between ART1 and six dimensions of tumor stemness unearthed intriguing associations." (PMID 38911388, 2024). "Another interesting target to add to the medicinal arsenal against cancer is an enzyme called ART-1 which is expressed on tumor cells." (PMID 40584631, 2025). "The expression levels of gp130 and the downstream targets c-Myc, cyclin D1 and Bcl-xL and the p-STAT3/STAT3 ratio were lower in the ART1-sh-transplanted tumours than in the NC tumours (P < 0.01)." (PMID 38504172, 2024). "Lastly, the intricate interplay between ART1 and the tumor microenvironment necessitates further exploration through rigorous experimental studies." (PMID 38911388, 2024). "These intricate correlations highlight the potential involvement of ART1 in modulating tumor stemness dynamics, shedding light on its role in cancer progression and metastasis." (PMID 38911388, 2024). "The expression levels of ART1 and gp130 in tumour tissue were also positively correlated (P < 0.01)." (PMID 38504172, 2024). "In summary, our study sheds light on the intricate relationship between ART1 expression levels, tumor prognosis, and the extent of immune infiltration across a spectrum of cancers." (PMID 38911388, 2024). "Our findings revealed distinct expression patterns of ART1 between tumor and normal tissues, highlighting its close correlation with clinical prognosis, immune-related genes, RNA modification genes, tumor stemness, and clinical phenotypes." (PMID 38911388, 2024). "The aims of this study were to investigate the effects of ART1 knockdown on IL-6-induced cell proliferation in vitro and use an in vivo murine model to observe the growth of transplanted tumours." (PMID 38504172, 2024). "Correspondingly, ART1 blockade with a therapeutic monoclonal antibody (22C12) reduced the growth and dissemination of ART1 expressing tumours in mice and promoted tumour infiltration of activated P2X7R+ CD8 T cells." (PMID 38022596, 2023). "Further studies are warranted in other tumor models to study the role of ART1 as a regulator of immunosuppression in the TME." (PMID 36829496, 2023). "In mouse non-small cell lung cancer and melanoma models, genetic and antibody-mediated Art1 inhibition slowed tumor growth in a CD8+ T cell-dependent manner, which was related to the increased infiltration of activated P2X7+CD8+ T cells in the tumor." (PMID 38273855, 2023). "In non-small cell lung cancer (NSCLC), ART1 expressed by tumour cells has been characterized as a novel pathway of immune escape." (PMID 38022596, 2023). "al. has recently shown a novel role of tumor cells expressing mono-ADP-ribosyl transferase 1 (ART1) in triggering immunosuppression in pre-clinical mouse models of NSCLC and melanoma." (PMID 36829496, 2023). "This intriguing association suggests that ART1 might exert influence over the immune landscape within the TME, positioning it as a potential target for novel tumor immunotherapeutic strategies." (PMID 38911388, 2024). "Furthermore, the robust correlation observed between ART1 and immune checkpoints suggests that ART1 holds promising potential as an optimal target for tumor immunotherapy." (PMID 38911388, 2024). "This underscores ART1 as a promising candidate for targeted tumor immunotherapy." (PMID 38911388, 2024). "Moreover, mice transplanted with ART1-sh CT26 cells that had high levels of IL-6 displayed tumours with smaller volumes (P < 0.05)." (PMID 38504172, 2024). "This emphasizes the pivotal role of ART1 in shaping the landscape of tumor immunotherapy." (PMID 38911388, 2024).
tumor (continued). "The intricate interplay observed between ART1 expression, immune cell types, and genomic features further accentuates the potential significance of ART1 as a central player in tumor immunology and a promising target for optimizing the outcomes of immunotherapy interventions." (PMID 38911388, 2024). "Furthermore, ART1 knockdown significantly suppressed tumour growth, as evidenced by a decreased tumour volume." (PMID 38504172, 2024). "The recent discovery of how tumour-expressed ART1 allows tumours to co-opt the immune homeostatic mechanism of NICD suggests that targeted ART1-inhibition would counter this immune escape mechanism and maintain the viability of critical anti-tumour immune cells." (PMID 38022596, 2023). "Notably, individuals exhibiting elevated ART1 expression levels were more inclined to exhibit favorable responses to immunotherapy (P < 0.05), thereby accentuating the pivotal role of ART1 in the context of tumor immunotherapy." (PMID 38911388, 2024). "Interestingly, inhibiting ART1 expression by genetic ablation or blocking ART1’s enzymatic activity using a humanized monoclonal activity triggered a robust antitumor immune response, which resulted in a significant reduction in tumor burden." (PMID 36829496, 2023). "Among ARTC family, ART1 and ART3 modulate the phosphoinositide 3-kinase (PI3K)/protein kinase B (AKT) pathway, influencing angiogenesis, tumor growth, and immune evasion via cluster of differentiation 8+ (CD8+) T-cell apoptosis." (PMID 41930181, 2026). "We delved into the correlation between ART1 expression and clinicopathological characteristics, including gender, stage, grade, and TNM, utilizing clinical data from diverse tumor samples." (PMID 38911388, 2024). "In the tumour context, we have demonstrated that NICD of P2X7R+ CD8 T cells following exposure to recombinant ART1 is exacerbated in the presence of CD38-blocking antibodies." (PMID 38022596, 2023). "Analyzing ART1 expression across diverse clinical samples within each tumor type yielded no discernible differences in ART1 levels among the 11 tumor types." (PMID 38911388, 2024). "The target receptor of ART1, namely the P2X7 receptor, is expressed across various immune cell subsets, including T cells, and plays a pivotal role in orchestrating inflammatory responses and anti-tumor immunity." (PMID 38911388, 2024). "The role of BCP on ART1 on glycolysis and energy metabolism has been shown in CT26 cells cultured and exposed to high-glucose conditions and in STZ-induced BALB/c mice transplanted CT26 tumor cell." (PMID 32998300, 2020). "The present study demonstrated that ART1 knockdown significantly inhibited IL-6-induced p-STAT3 and its target proteins, c-Myc, cyclin D1 and Bcl-xL (amp and E, 3 A-D, 7D & E), the proliferation of CRC cells and the growth of transplanted tumours in a mouse model." (PMID 38504172, 2024). "However, ART1 did not exhibit significant differences in relation to tumor grade across pan cancers." (PMID 38911388, 2024). "BCP-induced reduction in the expression levels of ART1 via NF-κB indicates that ART1 is an attractive therapeutic target and BCP may be an attractive molecule for controlling cell proliferation, apoptosis, energy metabolism, tumor growth along with regulating metabolic pathways." (PMID 32998300, 2020).
cancer (3 papers, 2024 to 2025). A tumor composed of atypical neoplastic, often pleomorphic cells that invade other tissues. "In this study, we aim to investigate the potential of actinomycete-derived bioactive compounds as inhibitors of ART1, a key enzyme implicated in cancer progression." (PMID 40864788, 2025). "Future research endeavors will focus on elucidating the intricate molecular mechanisms underlying ART1's interactions within the TME to unveil its full therapeutic potential in cancer management." (PMID 38911388, 2024). "Our prognostic analyses unveiled significant associations between ART1 expression levels and clinical outcomes in several cancer types." (PMID 38911388, 2024). "Subsequently, our investigation delved into the correlations between ART1 expression and various clinicopathological characteristics, aiming to unravel the intricate associations between ART1 and the clinical manifestations of cancer." (PMID 38911388, 2024). "These intricate associations highlight the potential regulatory role of ART1 in modulating diverse RNA modification pathways across various cancer types, suggesting its involvement in the complex landscape of cancer pathogenesis and progression." (PMID 38911388, 2024). "These comprehensive analyses provide valuable insights into the genetic landscape and mutation patterns associated with ART1 across various cancer types." (PMID 38911388, 2024). "Leveraging the powerful cBioPortal tool, we meticulously explored the mutation patterns of ART1 across a myriad of human cancers, uncovering its involvement in mutational events spanning multiple cancer types." (PMID 38911388, 2024). "The expression of m1A genes displayed a positive association with ART1 across various cancers, including UVM, PRAD, CESC, SARC, READ, KIPA, and GBM LGG." (PMID 38911388, 2024). "Notably, the association between ART1 expression and m5C genes remained consistent across different cancers." (PMID 38911388, 2024). "This study highlights the potential of these actinomycete-derived compounds as anticancer agents targeting ART1, offering a promising avenue for future research and development of novel cancer therapies." (PMID 40864788, 2025). "ART1, a glycosylphosphatidylinositol (GPI)-anchored tumor cell surface protein, has been implicated in cancer progression." (PMID 40864788, 2025). "Based on the results obtained in this study, we demonstrate the potential of actinomycete-derived bioactive compounds as inhibitors of ART1, a critical enzyme involved in cancer progression." (PMID 40864788, 2025). "Among these, the ART1 protein plays a critical role in promoting cancer progression, establishing it as a key target for drug therapy." (PMID 40864788, 2025). "This study marks the first comprehensive exploration of ART1's involvement across diverse cancer types." (PMID 38911388, 2024). "These compelling observations underscore the nuanced differential expression patterns of ART1 across a spectrum of cancers, suggesting a potential pivotal role for ART1 in the intricate landscape of carcinogenesis." (PMID 38911388, 2024). "This study employed extensive transcriptional datasets sourced from the TCGA database to meticulously investigate the intricate interplay between ART1 expression and a spectrum of factors across diverse cancers." (PMID 38911388, 2024). "These intricate correlations provide valuable insights into the multifaceted interplay between ART1 expression and immune cell infiltration across diverse cancer types." (PMID 38911388, 2024). "Through meticulous analysis, we elucidated a close interplay between ART1 and RNA modification genes, notably m1A, m5C, and m6A, across a broad spectrum of cancers." (PMID 38911388, 2024). "Nevertheless, despite these insights, a noticeable gap persists in our understanding of ART1 expression across diverse cancers, particularly concerning its implications for patient prognosis, survival, and its interplay within the TIME." (PMID 38911388, 2024).
cancer (continued). "These intricate correlations unveil the multifaceted interplay between ART1 expression and crucial immune-related parameters across various cancer types, underscoring its potential significance in the realm of cancer immunotherapy." (PMID 38911388, 2024). "Concurrently, we uncovered a notable correlation between ART1 expression and immunologic infiltration spanning 22 cancers." (PMID 38911388, 2024). "This study marks the pioneering bioinformatic exploration of ART1 across pan-cancer, focusing on prognosis and the TME for the first time." (PMID 38911388, 2024). "In this comprehensive study, we conducted a thorough assessment of the prognostic implications of ART1 across a diverse spectrum of cancers, shedding light on its potential as a robust prognostic biomarker for various malignancies." (PMID 38911388, 2024). "In addition, OS, DSS, DFI, and PFI Kaplan-Meier curve analysis showed that underscored ART1 as a protective factor across all cancers." (PMID 38911388, 2024). "Additionally, a significant correlation was observed between ART1 expression and cancer stage in STES (P < 0.05)." (PMID 38911388, 2024). "Our comprehensive analyses revealed notable associations between ART1 and a plethora of immune-related genes, with the majority exhibiting a negative correlation with ART1 across diverse cancers." (PMID 38911388, 2024). "The results showed that compared with the control, ART1-sh cancer cells induced by IL-6 exhibited reduced viability, a lower rate of colony formation, less DNA synthesis, decreased protein levels of gp130, c-Myc, cyclin D1, Bcl-xL, and a reduced p-STAT3/STAT3 ratio (P < 0.05)." (PMID 38504172, 2024). "Given the pivotal role of the immune system in cancer development and treatment response, conducting a comprehensive pan-cancer analysis to elucidate the immunologic effects of ART1 becomes imperative for identifying cancer types that could potentially benefit from anti-ART1 immunotherapy." (PMID 38911388, 2024). "These compelling findings collectively underscore the intricate involvement of ART1 in modulating immune responses within the TME and position it as a promising target for enhancing the efficacy of immunotherapeutic interventions in cancer treatment." (PMID 38911388, 2024). "Moreover, positive correlations emerged between ART1 expression and MSI in seven cancer types, including GBM, GBMLGG, and CESC, while negative correlations were observed in STES, KIPAN, STAD, and HNSC." (PMID 38911388, 2024).
adenocarcinoma (2 papers, 2007 to 2023). A common cancer characterized by the presence of malignant glandular cells. "We found that one week after the initiation of RT, the GTV decreased by 5.86%, 1.07%, and 20.95% in the adenocarcinoma, SCC, and SCLC groups, respectively, compared to that with ART1." (PMID 37761323, 2023). "In a subgroup analysis for the adenocarcinoma group, average reduction in V20 from ART1 to ART2, 3, and 4 was −2.98%, −9.06%, and −9.57%, respectively." (PMID 37761323, 2023). "However, despite the consistent decrease in ART1–4 levels in the adenocarcinoma and SCC groups, not all parameters showed significant results." (PMID 37761323, 2023). "In both the adenocarcinoma and SCC groups, there were no statistically significant changes in heart V20, V30, and Dmean values when comparing ART1 to ART4." (PMID 37761323, 2023).
ART1 also shares sentences with these, for which no sentence is quoted: diabetes (2 papers); lupus (2); adenoma (1); follicular adenomas (1); glioblastoma (1); glomerulonephritis (1); hepatocellular carcinoma (1); lupus nephritis (1); lymphopenia (1); non-small cell lung carcinoma (1); Obesity (1); Pan (1); papillary carcinoma (1).